MMP3 (matrix metallopeptidase 3)
Diseases named in the same sentence as MMP3 in open-access papers (continued):
Sharing a sentence is not in itself a finding about the gene and the disease.
Lung Injury (3 papers, 2013 to 2025). "Furthermore, it has been shown that following a traumatic brain injury, MMP-3 levels can also increase and cause additional damage to the blood–brain barrier." (PMID 35010191, 2021).
Marfan syndrome (3 papers, 2014 to 2024). A disorder of the connective tissue. "The MMP-3 gene showed significant up-regulation in dissection patients with Marfan syndrome in comparison with control patients (Ln2α = 2.22, p = 0.046)." (PMID 24720641, 2014). "Although none of these studies reported independent associations between circulating MMP-3 and cfPWV, 1-year treatment with perindopril, compared to placebo, was associated with a significant reduction in cfPWV as well as in plasma MMP-2 and plasma MMP-3 in 17 patients with Marfan Syndrome." (PMID 29070037, 2017).
metabolic syndrome (3 papers, 2020 to 2022). A cluster of metabolic risk factors for CARDIOVASCULAR DISEASES and TYPE 2 DIABETES MELLITUS. "Therefore the primary objectives of the current study was to evaluate the interaction between dietary total antioxidant capacity and rs2010963 polymorphism to affect components of metabolic syndrome, adiponectin and matrix metallo-proteinase (MMP)-3 in patients with metabolic syndrome." (PMID 32160900, 2020). "MMP-3 levels and MMP-3/TIMP-1 ratio were positively correlated with systolic blood pressure (SBP) or diastolic blood pressure (DBP) in obese and metabolic syndrome people." (PMID 34625635, 2021). "The aim of this study is to investigate the plasma levels of MMP-1, MMP-2, MMP-3, MMP-9, TIMP-1, TIMP-2 and their ratios in a large variety of study groups including overweight people and obese people with or without metabolic syndrome and non-obese healthy people with total of 479 participants." (PMID 34625635, 2021).
metastatic melanoma (3 papers, 2007 to 2023). A melanoma that has spread from its primary site to another anatomic site. "High expression levels of MMP-3 in human patients have been reported to be correlated with shorter disease-free survival in human metastatic melanoma." (PMID 36445856, 2022).
Myocardial fibrosis (3 papers, 2013 to 2022). "The levels of myocardial fibrosis markers (MMP-3, collagen, tumor growth factor (TGF-β), vascular endothelial growth factor (VEGFA), and procollagen I C-terminal propeptide (PICP)) were assessed in patients of both groups." (PMID 34088886, 2021). "In our study, we demonstrated relationships between tEAT and levels of pro-inflammatory cytokines (TNF-α and IL-6), adipokines (leptin and adiponectin), and markers of myocardial fibrosis (MMP-3, TGF-β, and collagen)." (PMID 34088886, 2021).
non-small cell lung carcinoma (3 papers, 2013 to 2023). A group of at least three distinct histological types of lung cancer, including non-small cell squamous cell carcinoma, adenocarcinoma, and large cell carcinoma. "In non-small cell lung cancer H460 and A549 cells, LicA could suppress migration and invasion through a reduction in MMP-1 and MMP-3 expression." (PMID 36840005, 2023). "MMP3 expression has been shown to be regulated at the transcriptional level through the mitogen-activated protein kinase- (MAPK-) AP1 pathway in human chondrocytes and in non-small-cell lung carcinoma cells." (PMID 34222497, 2021).
oral submucous fibrosis (3 papers, 2010 to 2025). "They studied 362 patients with oral submucous fibrosis (OSMF)and head and neck lesions and they concluded that the expression of MMP-3 genotype associated with 5A alleles may have an important role in the susceptibility of the patients to develop OSMF and head and neck squamous cell carcinoma." (PMID 21211041, 2011). "In contrast, in our study on naringenin's antifibrotic effects in oral submucous fibrosis (OSMF) focuses on molecular targets such as MMP2, MMP3, MMP9, TGFB1, ESR1, and SERPINE1, which are crucial in ECM remodeling and inflammation." (PMID 40575446, 2025).
pancreatic ductal adenocarcinoma (3 papers, 2020 to 2024). An infiltrating adenocarcinoma that arises from the epithelial cells of the pancreas. "Altogether, our results suggested a new signaling axis of KrasG12D/CCL9/MMP14 and MMP3 to initiate pancreatic ductal adenocarcinoma through promoting ADM in the pancreas." (PMID 38731942, 2024).
primary open-angle glaucoma (3 papers, 2022 to 2025). "Ussa and co-workers investigated whether the SNPs of the genes encoding MMP1, MMP2, MMP3, MMP9, and MMP17 were related to the response to latanoprost in 124 Spanish patients with open-angle glaucoma." (PMID 39769228, 2024).
pulmonary TB (3 papers, 2017 to 2021). "Our group and others demonstrated the involvement of MMP-1, the major human collagenase, and its activator MMP-3 (stromelysin-1) in driving pathology in pulmonary TB." (PMID 28596772, 2017). "MMP-1 and its activator MMP-3 were found to be related to the TB disease severity and treatment efficacy, while MMP-13 together with TIMP-2 were proved to be potential indicators of extra-pulmonary TB in adults." (PMID 33923293, 2021).
renal carcinoma (3 papers, 2012 to 2022). A carcinoma arising from the epithelium of the renal parenchyma or the renal pelvis. "sFRP-2 activated the Wnt pathway and promoted renal cancer growth whereas sFRP-3 expression induced the MMP-3 and ANGPT1 genes in renal cancer and thus contributed to the invasive capability of RCC." (PMID 22325146, 2012). "The results showed that EIF4EBP1, FOXM1, PLG, and VWF were highly expressed in renal carcinoma compared with normal renal tissue, and ADAM8, CGN, G6PC, ITIH4, and MMP3 were low in expression in renal carcinoma compared with normal renal tissue." (PMID 33968297, 2021).
scoliosis (3 papers, 2012 to 2019). A congenital or acquired spinal deformity characterized by lateral curvature of the spine. "Other authors have evaluated the possibility that gene variants of IL-6 and MMPs might be associated with scoliosis and suggest that MMP-3 and IL-6 promoter polymorphisms constitute important factors for the genetic predisposition to scoliosis." (PMID 29435499, 2018). "Other authors have evaluated the possibility that gene variants of IL-6 and MMPs might be associated with scoliosis and suggests that MMP-3 and IL-6 promoter polymorphisms constitute important factors for the genetic predisposition to scoliosis." (PMID 22264320, 2012). "MMP-1 and MMP-3 immuno-positive cells and cell clusters were abundant in fissured and disrupted regions in herniated and degenerated discs in comparison to (scoliosis) controls, and thus were comparable to unconstrained explant tissues." (PMID 31871771, 2019).
skin squamous cell carcinoma (3 papers, 2015 to 2025). A carcinoma arising from the squamous cells of the epidermis. "A protective role for MMP-3 has also been seen in skin squamous cell carcinoma." (PMID 25848906, 2015).
spondylitis (3 papers, 2019 to 2026). The inflammation of a vertebra. "On the other hand, significant correlations were found between IL-22 and Bath Ankylosing Spondylitis Functional Index (BASFI), Bath Ankylosing Spondylitis Patient Global Score (BASG1), Health Assessment Questionnaire (HAQ), Visual Analog Scale (VAS pain); MMP3 and mSASSS; MMP3 and hsCRP." (PMID 31440510, 2019).
vitiligo (3 papers, 2013 to 2020). Generalized well circumscribed patches of leukoderma that are generally distributed over symmetric body locations and is due to autoimmune destruction of melanocytes. "Moreover, vitiligo melanocytes produced many biologically active proteins among the senescence-associated secretory phenotype (SAPS), such as interleukin-6 (IL-6), matrix metallo proteinase-3 (MMP3), cyclooxygenase-2 (Cox-2), insulin-like growth factor-binding protein-3 and 7 (IGFBP3, IGFBP7)." (PMID 23555779, 2013).
adrenal tumors (2 papers, 2017). "Elevated expression of matrix metalloproteinase-3 (MMP-3) is associated with squamous cell carcinoma of the head and neck, and adrenal tumors." (PMID 28825646, 2017).
allergic disease (2 papers, 2021 to 2022). An immune response that occurs following re-exposure to an innocuous antigen, and that requires the presence of existing antibodies against that antigen. "We have not clearly proved the role of MMP-3 protein in the case of allergy to Hymenoptera venom." (PMID 33920429, 2021). "However, a comparison of ROC curves for all significant proteins showed that MMP-3, sCD30/TNFRSF8, sTNF-R1 are not significantly different from each other as prognostic factors of allergy." (PMID 33920429, 2021).
ANCA associated vasculitis (2 papers, 2015 to 2021). "Furthermore, diminished serum MMP-3 was also presented in patients with antineutrophil cytoplasmic antibody (ANCA)-associated vasculitis (AAV) treated with rituximab." (PMID 25190551, 2015). "The aim of the study was to evaluate the significance of metalloproteinase 3 (MMP-3), chemokine CXC ligand 13 (CXCL-13) and complement component 5a (C5a) in different stages of ANCA associated vasculitis (AAV)." (PMID 33664330, 2021).
aortic stenosis (2 papers, 2011 to 2017). Aortic valve stenosis is a aortic valve disease caused by the incomplete opening of the aortic valve. "Based on the microarray data, we chose three genes known to be mechanosensitive and associated with aortic stenosis: MMP-1, MMP-3, and IL-6." (PMID 21876831, 2011). "In addition, serum MMP-9, but also MMP-3 and TIMP-1, was correlated with invasive aortic PWV measurements in patients with aortic stenosis." (PMID 29070037, 2017).
Arrhythmia (2 papers, 2021 to 2023). Any cardiac rhythm other than the normal sinus rhythm. "Indeed, two studies reported positive correlation between high MMP-3 concentrations and ventricular arrythmias." (PMID 37189412, 2023).
Atrophy (2 papers, 2025). Any weakening or degeneration, especially through lack of use. "In both cases, IL-17 signaling is amplified, which drives extracellular matrix degradation (via upregulation of Mmp3/Mmp13) that culminates in colonic atrophy." (PMID 40356657, 2025).
brain tumors (2 papers, 2023 to 2024). "To further examine the impact of GMPPB and MMP3 knockdown in GBM tumors in a microenvironment similar to human brain tumors, we will expand our work to patient-derived orthotopic xenografts (PDOX) models as we have previously performed." (PMID 37834154, 2023). "Our objective is to validate four plasma biomarkers – glial fibrillary acidic protein (GFAP), neurofilament light (NEFL), matrix metalloprotease 3 (MMP3) and fatty acid binding protein 4 (FABP4) – and compare them with established brain tumor molecular markers and survival." (PMID 38879494, 2024).
bronchiolitis obliterans syndrome (2 papers, 2018 to 2019). A lung disorder that is mainly associated with chronic allograft dysfunction after lung transplantation and that is characterized by inflammation and fibrosis of bronchiolar walls that reduce the diameter of the bronchioles and result in progressive and irreversible airflow obstruction. "In transplantation, MMP3 has been linked to chronic transplant nephropathy and bronchiolitis obliterans syndrome after kidney and lung transplantation, respectively." (PMID 31849957, 2019). "This MS-driven proteomic study with subsequent ELISA verification identified high plasma levels of MMP3 to be associated with bronchiolitis obliterans syndrome post transplantation." (PMID 30297859, 2018).
calcification (2 papers, 2018 to 2021). Process by which organic tissue becomes hardened by the physiologic deposit of calcium salts. "In the literature, there are data on the association of MMP-3 with vascular calcification." (PMID 34205079, 2021). "MMP3 is present and enzymatically active in coronary plaques, and MMP3 polymorphisms are associated with the initiation and progression of these plaques, with plaque instability as well as with coronary calcification." (PMID 30563576, 2018).
carcinoid (2 papers, 2022). "Two genes (MMP3 and SNAI2) were differently expressed regarding the carcinoid tumor." (PMID 36553576, 2022).
cardiomyopathies (2 papers, 2021 to 2025). "The review identified key gene variants affecting athletic performance: endurance (AMPD1, PPARGC1A), power (ACTN3, NOS3), strength (PPARG), and injury susceptibility (COL5A1, MMP3), while also examining inherited conditions like cardiomyopathies (MYH7, MYBPC3)." (PMID 40724525, 2025). "Ablation of a specific MMP can lead to compensatory effects, thus we next examined expression of Mmp3, which belongs to the stromelysin family, as well as examining MMP-10, Mmp2 and Mmp9, the two major MMP gelatinases that have been associated with DMD cardiomyopathy." (PMID 34947929, 2021).
carotid atherosclerosis (2 papers, 2016 to 2023). A thickening and loss of elasticity of the walls of carotid arteries that occur with formation of atherosclerotic plaques. "High circulating MMP-3 levels are associated with coronary and carotid atherosclerosis progression." (PMID 37759829, 2023). "However, MMP-1 2G/2G homozygotes and MMP-3 polymorphisms were shown to synergistically lead to an increase in carotid atherosclerosis (odds ratio (OR) 3.31, p = 0.004)." (PMID 27529234, 2016). "Studies have consistently noted a role for MMP-3 in progression of carotid atherosclerosis." (PMID 27529234, 2016). "In conclusion, patients with established carotid atherosclerosis presented with exaggerated CAVI, MMP-3, MMP-7 MMP-9, and TIMP-1 levels compared to individuals without carotid atherosclerotic plaques." (PMID 37759829, 2023). "In the present study, patients requiring carotid revascularization appeared with higher levels of CAVI, MMP-3, MMP-7 MMP-9, and TIMP-1 compared to patients with carotid atherosclerosis under conservative treatment or controls without carotid atherosclerosis." (PMID 37759829, 2023).
carpal tunnel syndrome (2 papers, 2013 to 2020). Entrapment of the median nerve in the wrist that is characterized by numbness, tingling and painful movement. "DNA variants located within MMP1 (rs1799750), MMP3 (rs3025058, rs679620, rs591058, rs650108), MMP10 (rs486055), and MMP12 (rs2276109), have independently and/or in combination been associated with Achilles tendinopathy (AT) risk, Carpal Tunnel Syndrome (CTS) and ACL ruptures." (PMID 32650441, 2020).
celiac disease (2 papers, 2022 to 2023). An autoimmune genetic disorder with an unknown pattern of inheritance that primarily affects the digestive tract. "MMP3 as well as their inhibitors play a crucial role in the maintenance of extracorpuscular matrix homeostasis, which is expressed at high levels in the intestine of clinical IBD and celiac diseases." (PMID 36846248, 2023).
cerebral infarction (2 papers, 2020 to 2024). An ischemic condition of the brain, producing a persistent focal neurological deficit in the area of distribution of the cerebral arteries. "We demonstrated that MMP-3 KO reduces cerebral infarct size and is accompanied by global transcriptional changes." (PMID 39000490, 2024). "In this study, vx-765 treatment enhanced the expression levels of TIMP-1 and TIMP-2 but reduced the expression levels of MMP-1, MMP-2, MMP-3, and MMP-9 proteins after cerebral infarction." (PMID 33584203, 2020).
cholangiocarcinoma (2 papers, 2016 to 2017). A carcinoma that arises from the intrahepatic biliary tree (intrahepatic cholangiocarcinoma) or from the junction, or adjacent to the junction, of the right and left hepatic ducts (hilar cholangiocarcinoma). "To identify the mechanism underlying the effects of β6 on invasion in cholangiocarcinoma cells, we measured the mRNA expression of uPA, MMP2, MMP3, and MMP9 using quantitative real-time PCR after silencing or overexpressing β6." (PMID 27440504, 2016). "Our results showed that β6 induced the expression of MMP9 but not that of uPA, MMP2 or MMP3 in cholangiocarcinoma cells." (PMID 27440504, 2016).
cholesteatoma (2 papers, 2007 to 2012). A pathologic process characterized by the proliferation of keratinizing squamous epithelium resulting in the accumulation of keratin and cells in the middle ear and/or mastoid. "Additionally to these two isoforms, MMP1 and MMP3 activity in cholesteatomas were also assessed through zymography, and increased activity was seen only in the first isoenzyme." (PMID 22714856, 2012). "Specific cholesteatoma MMP isoenzymes (MMP2, MMP3, and MMP9) were first identified in 199617 with the use of immunohistochemistry tests." (PMID 22714856, 2012).
cognitive decline (2 papers, 2015 to 2025). "Furthermore, in blood plasma, MMP-3 levels were higher in men than women, with a sex-specific difference noted in the association between plasma MMP-3 levels and cognitive decline—lower MMP-3 was associated with less cognitive decline in women, but not in men." (PMID 38935232, 2025).
colorectal adenocarcinoma (2 papers, 2015 to 2020). The most common type of colorectal carcinoma. "There was a marked co-expression correlation significance between MMP3 and CCN2/CTGF (y = 0.08x + 0.1, R2 = 0.06) in the colorectal adenocarcinoma cases, suggesting that MMP3 may positively regulate CCN2/CTGF expression in both human clinical tumors and mouse cancers." (PMID 32260433, 2020). "We next examined the co-expression correlation between MMP3 and CCN2/CTGF among 632 tumor samples derived from 632 colorectal adenocarcinoma patients registered in The Cancer Genome Atlas (TCGA)." (PMID 32260433, 2020).
complication (2 papers, 2015 to 2017). Any disease or disorder that occurs during the course of, or because of, another disease, treatment, or procedure. "After adjustment for potential confounders and presence of vascular complications, circulating MMP-3 was associated with cfPWV [β per 1 SD higher lnMMP3 0.29 m/s (0.02; 0.55)]." (PMID 29070037, 2017). "Levels of HbA1c, LDL, triglycerides, MMP-1, MMP-2, MMP-3, MMP-9, MMP-10, TIMP-1 and markers of LGI and ED were significantly higher in individuals with vascular complications compared to those without." (PMID 25848912, 2015).
diabetic retinopathy (2 papers, 2021 to 2024). "The MMP3 gene expression exhibited an elevation in the stroma of diabetic retinopathy corneas." (PMID 39061775, 2024).
dilated cardiomyopathy (2 papers, 2020 to 2022). Cardiomyopathy which is characterized by dilation and contractile dysfunction of the left and right ventricles. "Also, in patients with advanced dilated cardiomyopathy, MMP-3 levels were undetectable suggesting that lower levels are associated with worse cardiac function." (PMID 32831121, 2020).
diverticulosis (2 papers, 2023 to 2025). "We observed a increased prevalence of the MMP3 −1715 5A allele surfaced among individuals with diverticulosis when juxtaposed with the control group." (PMID 38004080, 2023). "The MMP3 rs3025058 5A/5A genotype was nearly twice as frequent in patients with diverticulosis, while the 6A/6A genotype was only half as common in this group." (PMID 38004080, 2023). "Private haplotypes in individuals with diverticulosis included MMP3 −1715 5A/5A|MMP9 −1562 C/T|MMP12 −82 G/G (2%) and MMP3 −1715 6A/6A|MMP9 −1562 C/T|MMP12 −82 A/G (2%)." (PMID 38004080, 2023). "In our study, diverticulosis patients exhibited a lower frequency of the MMP3 rs3025058 6A/6A genotype in comparison with healthy controls." (PMID 38004080, 2023). "Among patients with diverticulosis, the most prevalent haplotypes included MMP3 −1715 5A/5A|MMP9 −1562 C/C|MMP12 −82 A/A (31%) and MMP3 −1715 5A/6A|MMP9 −1562 C/T|MMP12 −82 A/G (14%)." (PMID 38004080, 2023). "The frequency distribution of the MMP3 rs3025058 5A/5A genotype was nearly twice as high and the 6A/6A genotype was halved among patients with diverticulosis compared with the control group, although this difference was of borderline statistical significance for the entire model." (PMID 38004080, 2023). "The genes regulating ECM turnover, including TIMP1, MMP3, and MMP9, are involved in diverticulosis development." (PMID 40428403, 2025).